RN7SL5P (RNA, 7SL, cytoplasmic 5, pseudogene)
Synonyms: 7LEM1; formerly RN7SLP2; RN7SL249P
Gene: Miscellaneous RNA gene on chromosome 9 (9,442,060 to 9,442,380, forward strand). Ensembl gene ENSG00000265735.
Homologues: Orthologues: rabbit Metazoa_SRP (76% identical), rabbit Metazoa_SRP (67% identical), rabbit Metazoa_SRP (64% identical). Paralogues in human: RN7SL1 (83% identical), RN7SL2 (82% identical), RN7SL3 (82% identical), RN7SL4P (76% identical), RN7SL296P (75% identical), RN7SL230P (74% identical), RN7SL769P (74% identical), RN7SL126P (74% identical), RN7SL478P (74% identical), RN7SL14P (73% identical), RN7SL357P (73% identical), RN7SL45P (73% identical), and 699 more.
Diseases named in the same sentence as RN7SL5P in open-access papers:
RN7SL5P is named in the same sentence as 3 diseases in open-access papers, as found by Europe PMC text mining. Sharing a sentence is not in itself a finding about the gene and the disease. The quoted sentences say what the papers report.
adenoma (1 paper, 2024). A neoplasm arising from the epithelium. "Noteworthy, the numbers of RNA interactors of some MP-RNAs (WDR62, TGFBR3, RN7SL5P, RMRP, MIR663AHG, AJ009632.2, CDKL1, OPRD1, PLOD1, AL117692.1, ATP13A2, EPB41) in cancer tissue were significantly increased compared with that in paracancer and adenoma." (PMID 38773399, 2024).
prostate carcinoma (1 paper, 2024). A carcinoma that arises from epithelial cells of the prostate gland. "RN7SL5P, a long noncoding RNA, as well as other genes, was significantly upregulated in prostate cancer from AA men < 55 years compared to AA men ≥ 55 years." (PMID 38566104, 2024).
RN7SL5P also shares sentences with these, for which no sentence is quoted: cancer (1 paper).